GALNT5 (polypeptide N-acetylgalactosaminyltransferase 5)
Description:
Catalyzes the initial reaction in O-linked oligosaccharide biosynthesis, the transfer of an N-acetyl-D-galactosamine residue to a serine or threonine residue on the protein receptor. Has activity toward EA2 peptide substrate, but has a weak activity toward Muc2 or Muc1b substrates (By similarity).
Synonyms: GalNAc-T5; GALNACT5
Tractability: Antibody: UniProt predicts a signal peptide or a membrane-spanning region. PROTAC: ubiquitination databases record sites on it.
Gene: Protein-coding gene on chromosome 2 (157,257,578 to 157,318,491, forward strand). Ensembl gene ENSG00000136542.
Subcellular location: Golgi apparatus membrane
Subcellular location (Human Protein Atlas): Cytosol; Golgi apparatus; Nucleoli; Vesicles
Pathways (Reactome):
Metabolism of proteins: O-linked glycosylation of mucins
Gene Ontology:
Molecular function: polypeptide N-acetylgalactosaminyltransferase activity
Biological process: glycosaminoglycan biosynthetic process; protein O-linked glycosylation; protein O-linked glycosylation via N-acetyl-galactosamine
Cellular component: Golgi apparatus; Golgi membrane
Genetic constraint (gnomAD): Loss-of-function variants: 42 observed, 53.81 expected, observed/expected ratio (o/e) 0.78, 90% interval 0.61 to 1.01. The upper end of that interval is the gene's LOEUF score, 1.01, which puts it in group 4 of 6, group 1 being the genes least tolerant of losing a copy. Missense variants: 845 observed, 849.5 expected, observed/expected ratio (o/e) 0.99, 90% interval 0.94 to 1.05. Synonymous variants: 318 observed, 305.99 expected, observed/expected ratio (o/e) 1.04, 90% interval 0.95 to 1.14.
Homologues: Orthologues: chimpanzee GALNT5 (99% identical), macaque GALNT5 (95% identical), pig GALNT5 (83% identical), rabbit GALNT5 (82% identical), guinea pig GALNT5 (76% identical), mouse Galnt5 (74% identical), rat Galnt5 (74% identical), dog GALNT5 (65% identical), tropical clawed frog galnt5 (45% identical), Caenorhabditis elegans gly-5 (24% identical), Drosophila melanogaster Pgant9 (23% identical), Drosophila melanogaster Pgant5 (23% identical), and 1 more. Paralogues in human: GALNT10 (24% identical), GALNTL6 (23% identical), GALNT3 (23% identical), GALNT1 (23% identical), GALNT2 (23% identical), GALNT6 (23% identical), GALNT4 (23% identical), GALNT13 (22% identical), GALNT14 (22% identical), GALNT16 (22% identical), GALNT11 (22% identical), GALNT12 (21% identical), and 7 more.
Diseases named in the same sentence as GALNT5 in open-access papers:
GALNT5 is named in the same sentence as 25 diseases in open-access papers, as found by Europe PMC text mining. Sharing a sentence is not in itself a finding about the gene and the disease. The quoted sentences say what the papers report.
gastric cancer (6 papers, 2016 to 2025). A primary or metastatic malignant neoplasm involving the stomach. "GALNT5 encodes a membrane-bound transferase in the Golgi and is reported to facilitate the proliferation and migration of colorectal and gastric cancer cells." (PMID 31828095, 2019). "GALNT5 (GalNAc transferase 5) mediates the carcinogenesis and progression of cholangiocarcinoma and gastric cancer." (PMID 40362181, 2025). "And GALNT5 uaRNA (UTR-associated RNA), a lncRNA, which is derived from the 3’-UTR of GALNT5 was confirmed to interact with HSP90 to promote gastric cancer progression." (PMID 39433745, 2024). "The expression of the 5 other genes were found to be repressed by over-expressed non-coding RNA or by aberrant methylation of the promoter: GALNT5 in gastric cancer, ADAM6 in lung adenocarcinoma, PIWIL1 and PIWIL4 in lung adenocarcinoma and renal cell carcinoma." (PMID 31568528, 2019). "Additionally, low intra-tumoral GALNT5 expression was detected in advanced stage gastric cancer patients with poor prognosis, and higher GALNT10 expression was found in diffuse type gastric cancers." (PMID 26848976, 2016).
breast carcinoma (4 papers, 2015 to 2024). "Two GALNT5 somatic missense mutations were found in primary breast cancers and functional testing revealed that these mutations reduced GALNT5 enzymatic activity." (PMID 26309160, 2015). "In breast cancers, presence of two missense mutations (p.E507D and p.L692F in the catalytic domain) of GALNT5 appeared to reduce the transferase activity of GalNAcT5." (PMID 27322213, 2016). "Like MUC1, breast cancer patients with overexpressed GCNT3 and GALNT5 predict worse survival, probably due to the worse drug response mediated by over-glycosylation." (PMID 35970845, 2022).
cholangiocarcinoma (4 papers, 2023 to 2025). A carcinoma that arises from the intrahepatic biliary tree (intrahepatic cholangiocarcinoma) or from the junction, or adjacent to the junction, of the right and left hepatic ducts (hilar cholangiocarcinoma). "Previous reports showed that GALNT5 promotes cholangiocarcinoma carcinogenesis and progression through EGFR/AKT/ERK signaling." (PMID 39433745, 2024). "GALNT5, for instance, has been shown to promote an invasive phenotype in cholangiocarcinoma (CCA) cells that previously expressed it at low levels." (PMID 37367731, 2023). "The GALNT5 gene, part of the GALNT family, enhances EGF/EGFR activation in cancers like cholangiocarcinoma, hepatocellular carcinoma, and ovarian cancer." (PMID 40739397, 2025).
colorectal cancer (3 papers, 2019 to 2020). A primary or metastatic malignant neoplasm that affects the colon or rectum. "Interestingly, hsa-miR-196b-5p was also found to molecularly interact with HOXB7 and GALNT5 and inhibit their expression in colorectal cancer." (PMID 33333738, 2020).
hepatoblastoma (2 papers, 2016 to 2018). Hepatoblastoma (HB) is a malignant hepatic tumor and is the most common pediatric liver cancer. "Cytogenetic data of hepatoblastoma have revealed that up-regulation of GALNT5, DAPL1, ERMN, SCN1A and SCN3A plays a major role in the development and progression of the disease." (PMID 27322213, 2016). "Upregulation of GALNT5 played a major role in hepatoblastoma progression." (PMID 29970122, 2018). "However, the post-translational modifications regulated by GalNAcT5 in hepatoblastoma cells remain undefined, as the mechanism of action of DAPL1, ERMN, GALNT5, SCN1A and SCN3A genes." (PMID 27322213, 2016).
pancreatic adenocarcinoma (2 papers, 2024 to 2025). "The most compelling evidence comes from investigations of N-acetylgalactosaminyltransferase 5, encoded by GALNT5, a key enzyme that initiates mucin-type O-glycosylation and has been identified as a novel suppressor of ferroptosis in pancreatic adenocarcinoma." (PMID 41008983, 2025). "GALNT5 knockdown significantly curtails the proliferation, migration, and invasion of pancreatic adenocarcinoma cells, while concurrently promoting ferroptosis, establishing a direct functional connection between the O-glycosylation machinery and ferroptotic cell death resistance." (PMID 41008983, 2025). "High expressions of GALNT5 and GALNT10 are positively correlated with pancreatic cancer survival, while expressions of GALNT8 AND GALNT10 are negatively correlated with survival in PAAD (pancreatic adenocarcinoma)." (PMID 39433745, 2024).
pancreatic cancer (2 papers, 2024 to 2025). "Combined with previous in vitro results, we suggest that GALNT5 confers chemotherapy resistance to FOLFIRINOX in pancreatic cancer cells by binding to MYH9 and inhibiting NOTCH signaling in vivo." (PMID 39433745, 2024). "We validated its expression in four Gene Expression Omnibus (GEO) datasets: GSE15471, GSE16515, GSE28735, and Ren Ji cohort (GSE102238) and confirmed that GALNT5 was more highly expressed in pancreatic cancer tissues." (PMID 39433745, 2024). "In summary, the potential mechanism by which GALNT5 affects FOLFIRINOX chemotherapy resistance in pancreatic cancer may be that it affects the HR repair process of DSB during chemotherapy." (PMID 39433745, 2024). "However, little research has been achieved on GALNT5 in pancreatic cancer." (PMID 39433745, 2024). "Among the nineteen UDEGs, other than the seven UDEGs reported to be carcinogenic and prometastatic genes involved in pancreatic cancer, the other UDEGs, such as ESM1, PCDH7, CORO2A, CEACAM5, GALNT5 and TMPRSS4, are also involved in other cancers." (PMID 40362181, 2025). "The survival map of the hazard ratio showed that only the expressions of GALNT5, GALNT8, GALNT10, and GALNT16 displayed significant differences in prognosis with pancreatic cancer." (PMID 39433745, 2024). "Meanwhile, it is worth noting that GALNT5, which is hardly ever reported in PDAC, is the only member in this family that is highly expressed in pancreatic cancer and has a worse prognosis compared with the low-expression group." (PMID 39433745, 2024).
leukemia (1 paper, 2015). A malignant (clonal) hematologic disorder, involving hematopoietic stem cells and characterized by the presence of primitive or atypical myeloid or lymphoid cells in the bone marrow and the blood. "This enhancer also has interactions with the promoter of GALNT5 and appears to be bound by a number of factors in K562 including GATA2, PML, TAL1 and BCL3, all of which have been implicated in the leukemia or other forms of cancer." (PMID 26576536, 2015).
liver fibrosis (1 paper, 2019). "Among the seven potential biomarkers FABP3, GALNT5, GPR84, ITGB6, MYEOV, PLEKHS1, and STRA6, we are particularly interested in GPR84 and STRA6 because they link to liver fibrosis that is a major risk factor in HCC and an independent risk factor of recurrence after hepatectomy." (PMID 31828095, 2019).
myelodysplastic syndrome (1 paper, 2023). A clonal hematopoietic disorder characterized by dysplasia and ineffective hematopoiesis in one or more of the hematopoietic cell lines. "In the complex genome of a case (BNGOHM-0000191) with myelodysplastic syndromes (MDS), OGM detected a 392.8 kbp tandem duplication on chr7, resulting in the duplication of KMT2C, GALNTT11, and GALNT5." (PMID 38137484, 2023).
prostate carcinoma (1 paper, 2025). A carcinoma that arises from epithelial cells of the prostate gland. "The tumor aggressiveness of prostate cancer cell lines has been linked to the expression of GALNT5 and ST3GAL6, mediating the synthesis of α2–3 sialic acids and especially sialyl-LewisA on MUCs in prostate cancer cell lines." (PMID 40885395, 2025).
schizophrenia (1 paper, 2022). A major psychotic disorder characterized by abnormalities in the perception or expression of reality. "Nevertheless, we found a number of genes in this list that have a reported association to schizophrenia or other neuropsychiatric disorders, for example, TENM4, NXN, NRXN1, GALNT5, SHANK3 and RELN." (PMID 36711134, 2022).
tumor (9 papers, 2019 to 2025). "We further explored them respectively in TCGA combined with GTXs and found that only GALNT5 has significantly high expression in tumor tissues compared with adjacent normal tissues and highly expressed GALNT5 suggests a worse prognosis in PAAD." (PMID 39433745, 2024). "Our results suggested that in the context of FOI treatment, compared with the vector group, the tumor was significantly enlarged after overexpression of GALNT5, while the tumor growth was significantly inhibited after continued knocking down MYH9." (PMID 39433745, 2024). "In this study, we identified GALNT5 as a potential therapeutic target in PDAC conferring tumor FOLFIRINOX resistance." (PMID 39433745, 2024). "Four genes were associated with the tumor stage, including solute carrier family 6 member 14 (SLC6A14), polypeptide N-acetylgalactosaminyltransferase 5 (GALNT5), tetraspanin 1 (TSPAN1), and islet amyloid polypeptide (IAPP)." (PMID 34591244, 2021). "Silencing GALNT5 reduces tumor proliferation, migration, and invasion." (PMID 40739397, 2025). "Moreover, GALNT5 was significantly related to tumor differentiation (III VS I-II), and lymph node metastasis, without relation to distant metastasis and AJCC stage." (PMID 39433745, 2024). "Moreover, relatively high level of GCNT3 and GALNT5 was observed in tumor tissues and predicted worse prognosis in patients from GEO database." (PMID 35970845, 2022). "Some of the glycoTs genes such as GCNT3, GALNT5, FUT3, B3GNT6 and B3GNT3 were more than 19-fold overexpressed in tumour samples." (PMID 32203219, 2020). "Furthermore, except for functions between the PDAC cells, GALNT5 was likely to enhance the NOTCH pathway, thus influencing the immune infiltration in the tumor microenvironment and CAFs to achieve drug resistance." (PMID 39433745, 2024). "We found that GALNT5 expression increased with increasing tumor grade, but not with individual cancer stage and nodal metastasis." (PMID 39433745, 2024).
cancer (8 papers, 2015 to 2025). A tumor composed of atypical neoplastic, often pleomorphic cells that invade other tissues. "The effects of the NOTCH pathway are vital in neuron growth, embryonic development, and cancer, while we have found that it was critical in GALNT5-induced drug resistance." (PMID 39433745, 2024). "Next, we analyzed some clinical events and several common gene mutants in PAAD of TCGA datasets based on GALNT5 expression via UALCAN (The University of Alabama at Birmingham Cancer Data Analysis Portal)." (PMID 39433745, 2024). "Additionally, CTRP (Cancer Therapeutics Response Portal) database was applied to detect the drug sensitivity of MUC1 and related glycosyltransferases to numerous clinical chemotherapeutics and found most of them were positively corelated with drug resistance, especially MUC1, GCNT3, and GALNT5." (PMID 35970845, 2022).
GALNT5 also shares sentences with these, for which no sentence is quoted: bladder cancer (1 paper); colon cancer (1); fibrosarcoma (1); glioma (1); hepatocellular carcinoma (1); lung adenocarcinoma (1); melanoma (1); neurodevelopmental disorder (1); pancreatic ductal adenocarcinoma (1); renal cell carcinoma (1); respiratory depression (1).